CHMP4C (charged multivesicular body protein 4C)
Diseases named in the same sentence as CHMP4C in open-access papers (continued):
Sharing a sentence is not in itself a finding about the gene and the disease.
osteosarcoma (2 papers, 2022 to 2024). A usually aggressive malignant bone-forming mesenchymal neoplasm, predominantly affecting adolescents and young adults. "Through its ability to heighten the phosphorylation of GSK3β and activate the Wnt/β-catenin signaling pathway, CHMP4C plays a pivotal role in fostering the invasion and metastasis of osteosarcoma." (PMID 38720781, 2024). "CHMP4C expression and signaling molecules in OS were assessed in osteosarcoma cell lines (MG63, U2OS, HOS) and hFOB1.19 cells using reverse transcription-quantitative polymerase chain reaction (RT-qPCR) and immunofluorescence staining." (PMID 38720781, 2024). "Overexpression of CHMP4C promoted the proliferation, migration and invasion of the osteosarcoma cell." (PMID 36244998, 2022). "The RT-qPCR showed that CHMP4C mRNA expression levels in the osteosarcoma cells were significantly increased compared to the osteoblasts." (PMID 36244998, 2022). "Consistent with this, RT-qPCR was performed to validate the high expressed CHMP4C in the osteosarcoma cell lines." (PMID 36244998, 2022). "We found that overexpression of CHMP4C enhanced the migratory and invasive abilities of osteosarcoma cells." (PMID 36244998, 2022). "Through the analysis of multiple public databases, CHMP4C was found to be up-regulated in a variety of tumors, including osteosarcoma." (PMID 36244998, 2022). "The expression level of CHMP4C was found to positively correlate with the risk score, while GSDMA was found to negatively correlate with the high risk of osteosarcoma, suggesting that CHMP4C may be a risk factor." (PMID 36244998, 2022). "Finally, overexpression of CHMP4C promoted the proliferation, migration and invasion of the osteosarcoma cell line U2OS." (PMID 36244998, 2022). "Similar to the results of our study, the high expression of CHMP4C might be related to the poor prognosis of osteosarcoma." (PMID 36244998, 2022). "In addition, the expression of CHMP4C was quantified in the osteoblasts and osteosarcoma cell lines." (PMID 36244998, 2022). "Compared with osteoblasts, the expression level of CHMP4C in osteosarcoma cells was up-regulated, which might be a promising biomarker." (PMID 36244998, 2022). "Finally, we identified a promising biomarker, CHMP4C, which is highly expressed in osteosarcoma." (PMID 36244998, 2022). "By the Lasso Cox regression analysis, 6 key PRGs were screened for constructing the optimal model, namely CHMP4C, GZMA, BAK1, CASP1, CASP6, and GSDMA, and a six PRGs signature was successfully constructed for osteosarcoma." (PMID 36244998, 2022).
viral infections (2 papers, 2021 to 2025). "CHMP4C has also been investigated in the context of viral infections, as viruses utilize similar cellular machinery." (PMID 40699655, 2025). "Like CHMP4C, VPS37B has been studied in the context of viral infections." (PMID 40699655, 2025).
lymph node metastasis (1 paper, 2023). "In lymph node metastasis, CHMP4C expression gradually increased as the number of lymph node metastases increased." (PMID 37388224, 2023).
non-small cell lung carcinoma (1 paper, 2015). A group of at least three distinct histological types of lung cancer, including non-small cell squamous cell carcinoma, adenocarcinoma, and large cell carcinoma. "Overall, our work discovers a novel action of CHMP4C in radiation resistance, suggesting CHMP4C as a new drug target for non-small cell lung cancer treatments." (PMID 26712741, 2015). "Together, our work establishes a new function of CHMP4C in radiation resistance, which will offer a potential strategy for non-small cell lung cancer by disrupting CHMP4C." (PMID 26712741, 2015).
renal carcinoma (1 paper, 2025). A carcinoma arising from the epithelium of the renal parenchyma or the renal pelvis. "Among 15 genes which downregulated in Ureteral sample, as well as the chromatin states closed in their potential regulatory sites, four genes (CEP170B, CHMP4C, KCNN4, and TJP2) are prognostic for renal cancer, that high expression is favorable." (PMID 40034749, 2025).
tumor (25 papers, 2015 to 2025). "Analysis of 21 paired LUSC tumor and adjacent normal tissues revealed that CHMP4C and PYGB were predominantly localized to the nucleus and cytoplasm of tumor cells, with positive immunoreactivity indicated by brown staining." (PMID 41180485, 2025). "In contrast, CHMP4C and PYGB were overexpressed in LUSC and associated with poor outcomes, implying roles in tumor progression and metastatic potential." (PMID 41180485, 2025). "This dual pattern highlights CHMP4C as a potential therapeutic target for enhancing anti-tumor immunity by limiting inhibitory signaling within the microenvironment." (PMID 41180485, 2025). "We found that high expression of CHMP4C in tumor environment tended to have a lower immune score suggesting less lymphoid T-cell infiltration." (PMID 37388224, 2023). "Notably, CAMK2A exhibited higher expression in normal lung tissues, whereas CHMP4C and PYGB were markedly overexpressed in LUSC, with their dysregulation associated with poorer clinical outcomes and a potential role in tumor progression and metastasis." (PMID 41180485, 2025). "RT-qPCR analysis of mRNA expression in tumor tissues revealed that compared to the empty vector group, CHMP4C overexpression significantly increased the expression of CHMP4C and β-catenin in mouse tumor tissues (p < 0.0001) and significantly decreased GSK3β expression (p < 0.001)." (PMID 38720781, 2024). "TPM3, CHMP4C, EEF1A1, FASN, TNF, S100A10, and IL1A represent a high-risk score and poor prognosis, suggesting that these genes may be associated with the tumor process in patients with CC and appear to be pro-oncogenes." (PMID 36685937, 2022). "CHMP4C and TNF, as high-risk genes for tumor promotion, positively correlate with promoting tumor progression immune-related cells such as activated mast cells and resting dendritic cells, and negatively correlate with protective immune-related cells such as naïve B cells and CD8+ T cells." (PMID 35574296, 2022). "Some studies show that CHMP4C plays an important regulatory role in the tumor cell cycle." (PMID 35783277, 2022). "CHMP4C may operate through signaling pathways that suppress immune responses or limit stromal cell proliferation, thereby fostering an immunosuppressive microenvironment favorable to tumor persistence." (PMID 41180485, 2025). "Prognostic genes including EZH2, PCNA, and BIRC5 were specifically expressed in epithelial clusters, while CHMP4C, ATP13A2, and ALDOA showed broader expression patterns, supporting their tumor-specific roles." (PMID 40678068, 2025). "Immunohistochemical evaluation confirmed markedly increased CHMP4C and PYGB expression in LUSC compared with adjacent non-tumor tissues (P < 0.001), while CAMK2A expression was significantly enriched in normal tissues (P < 0.001)." (PMID 41180485, 2025). "While three genes (AHNAK, ABCC9, and DIP2C) were highly expressed in normal tissues, eight genes (CHMP4C, CLIC3, DARS2, PLOD1, POU5F1, RAD9A, RUNX2, SLC3A2) were highly expressed in tumour tissues." (PMID 36685927, 2022). "Previous immune-related analyses in this paper showed that CHMP4C, TNF, and GZMB are all closely related to the tumor immune microenvironment." (PMID 35574296, 2022). "Through the HPA database, we found that three genes (ABCC9, AHNAK, and DIP2C) had low expression in patients with tumours, whereas eight genes (PLOD1, SLC3A2, RUNX2, RAD9A, CHMP4C, DARS2, CLIC3, and POU5F1) were highly expressed." (PMID 36685927, 2022). "Seven pyroptosis-related genes (ELANE, IL18, CHMP2B, CHMP4C, CASP9, CHMP6, and CHMP2A) were downregulated in tumor tissues, while 31 pyroptosis-related genes were upregulated in tumor tissues." (PMID 35432539, 2022). "We can find that the expression of GNG7, MXRA7, ASB2, and PDGFD in tumor samples is significantly lower than that in normal samples, while the expression of RPS6KA1, CHMP4C, APOL1, and LYPD3 is reverse." (PMID 36225190, 2022).
tumor (continued). "Contrary to the function of CHMP4C on cell fate, inhibition of ATM enhances ARF levels and stimulates the tumor-suppressive effects of ARF in human oncogene-transformed and cancer cells." (PMID 26712741, 2015). "Eight genes (SLC3A2, DARS2, DIP2C, PLOD1, RUNX2, ABCC9, AHNAK, and CLIC3) may be involved in the malignant transformation of tumours, and three genes (CHMP4C, POU5F1, and RAD9A) may have a protective effect in patients with tumours." (PMID 36685927, 2022). "Through the HPA database, we found that three genes, namely ABCC9, AHNAK, and DIP2C, had low expression in patients with tumours, and eight other genes—PLOD1, SLC3A2, RUNX2, RAD9A, CHMP4C, DARS2, CLIC3, and POU5F1—were highly expressed in patients with tumours." (PMID 36685927, 2022). "Specifically, CHMP4C, IRF9, and TRAF5 may function as tumor suppressors." (PMID 40893939, 2025). "Interestingly, PRGs with CNV gain, including GSDMD, GSDMC, CHMP4C and CHMP6, were significantly higher in HCC samples than in adjacent non-tumor samples (p < 0.001), suggesting that CNVs may regulate PRGs expression." (PMID 36650832, 2023).
cancer (18 papers, 2009 to 2025). A tumor composed of atypical neoplastic, often pleomorphic cells that invade other tissues. "CAMK2A displayed broad positive correlations, with distinct clusters of strong associations in several cancers, whereas CHMP4C and PYGB exhibited heterogeneous profiles characterized by both positive and negative associations." (PMID 41180485, 2025). "Interestingly, a polymorphism in the human ESCRT-III component CHMP4C, which impairs the abscission checkpoint, has been linked to increased cancer susceptibility." (PMID 41171097, 2025). "CHMP4C has been reported to be imbalanced in many cancers, but whether CHMP4C expression is associated with CC is still unknown." (PMID 32406588, 2020). "In this regard, recent studies have implicated ESCRT-III, specifically the CHMP4C subunit and VPS4, in cancer development." (PMID 38740816, 2024). "More studies are needed to elucidate the reasons for the differences in the roles of CHMP4C across different cancers in the future." (PMID 36509838, 2022). "Meanwhile, CHMP3 and CHMP4C were significantly stained in normal renal tissues, and the staining range was small in cancer tissues." (PMID 35845137, 2022). "In future work, it will be interesting to explore if the AKTIP association with the ESCRT machinery has an impact on cancer, which has been indicated for TSG101 and more recently reported for the ESCRT III subunit CHMP4C." (PMID 34449766, 2021). "CHMP4C transports the required endosomal sorting complex involved in cell division of daughter cells and plays a greatly significant role in many processes such as cancer pathogenesis and progression in the form of extracellular vesicles." (PMID 37388224, 2023). "CHMP4C has been proposed to be involved in the progression of different carcinomas." (PMID 37388224, 2023). "It has been found that CHMP4C has abnormal expression in cancer." (PMID 32406588, 2020). "Based on the role of CHMP4C in a variety of cell functions, research has begun to focus on whether it contributes to the progression of cancer." (PMID 32406588, 2020). "Moreover, CHMP4C might act as a cancer-promoting factor, which is expected to become an effective target for cancers." (PMID 36244998, 2022). "Furthermore, CHMP4C has been frequently overexpressed in human cancer tissue." (PMID 35620407, 2022). "The main types of copy number variations of pyroptosis genes in pan-cancer were heterozygous amplifications and deletions, among which the CNVs of CHMP4B, CHMP4C, and IL6 in most tumors were heterozygous amplifications." (PMID 36090967, 2022). "Genbank EST accession AA099748 aligns to the genome 3′ to the gene CHMP4C, along with the EST AW440175, both from cancer tissues." (PMID 19180177, 2009). "The IHC staining revealed that CHMP4C protein expression was predominantly localized in the nucleus and cytoplasm of cancer cells, whereas in normal tissues, CHMP4C was either weakly expressed or absent." (PMID 40893939, 2025). "The C-terminal tail of CHMP4C was recently shown to be bound by the apoptosis inhibitor PDCD6IP, suggesting that the cancer-specific splice form of CHMP4C may have altered binding behavior with PDC6IP." (PMID 19180177, 2009).
infection (3 papers, 2017 to 2022). The state of being infected such as from the introduction of a foreign agent such as serum, vaccine, antigenic substance or organism. "Comparison of genes differentially expressed in the four cell types before infection revealed high expression of CD4 in THP-1-derived macrophages and low expression of CHMP4C (charged multivesicular body protein 4C)." (PMID 28442752, 2017).
CHMP4C also shares sentences with these, for which no sentence is quoted: lung squamous cell carcinoma (4 papers); breast carcinoma (2); colorectal cancer (2); pancreatic cancer (2); benign prostatic hyperplasia (1); colon adenocarcinoma (1); copy number variation (1); COVID-19 (1); gastric cancer (1); glioma (1); hepatocellular carcinoma (1); lung adenocarcinoma (1); pancreatic adenocarcinoma (1); pancreatic ductal adenocarcinoma (1); thymoma (1).